TBC1D13 (TBC1 domain family member 13)
Description:
Acts as a GTPase-activating protein for RAB35. Together with RAB35 may be involved in regulation of insulin-induced glucose transporter SLC2A4/GLUT4 translocation to the plasma membrane in adipocytes.
Synonyms: FLJ10743
Tractability: PROTAC: ubiquitination databases record sites on it; its protein half-life has been measured.
Gene: Protein-coding gene on chromosome 9 (128,787,233 to 128,810,432, forward strand). Ensembl gene ENSG00000107021.
Subcellular location: Membrane; Cytoplasm
Subcellular location (Human Protein Atlas): Cytosol
Pathways (Reactome):
Vesicle-mediated transport: TBC/RABGAPs
Gene Ontology:
Molecular function: protein binding; GTPase activator activity; small GTPase binding
Biological process: regulation of cilium assembly; intracellular protein transport
Cellular component: cytoplasm; membrane; cytosol
Genetic constraint (gnomAD): Loss-of-function variants: 40 observed, 54.56 expected, observed/expected ratio (o/e) 0.73, 90% interval 0.57 to 0.95. The upper end of that interval is the gene's LOEUF score, 0.95, which puts it in group 4 of 6, group 1 being the genes least tolerant of losing a copy. Missense variants: 377 observed, 515.95 expected, observed/expected ratio (o/e) 0.73, 90% interval 0.67 to 0.8. Synonymous variants: 182 observed, 208.39 expected, observed/expected ratio (o/e) 0.87, 90% interval 0.77 to 0.99.
Homologues: Orthologues: chimpanzee TBC1D13 (99% identical), dog TBC1D13 (98% identical), mouse Tbc1d13 (98% identical), macaque TBC1D13 (96% identical), guinea pig TBC1D13 (96% identical), rat Tbc1d13 (95% identical), pig TBC1D13 (88% identical), tropical clawed frog tbc1d13 (82% identical), rabbit TBC1D13 (80% identical). Paralogues in human: TBC1D9 (22% identical), TBC1D9B (22% identical), TBC1D8 (22% identical), TBC1D8B (21% identical), TBC1D22A (20% identical), TBC1D16 (19% identical), TBC1D22B (19% identical), TBCK (18% identical), TBC1D17 (17% identical), TBC1D25 (17% identical), RABGAP1 (17% identical), TBC1D2B (17% identical), and 33 more.
Diseases named in the same sentence as TBC1D13 in open-access papers:
TBC1D13 is named in the same sentence as 4 diseases in open-access papers, as found by Europe PMC text mining. Sharing a sentence is not in itself a finding about the gene and the disease. The quoted sentences say what the papers report.
melanoma (3 papers, 2010 to 2022). A malignant, usually aggressive tumor composed of atypical, neoplastic melanocytes. "Seven prognosis associated TBCs genes including TBC1D13, TBC1D16, TBC1D7, TBC1D10C, TBC1D19, TBC1D8B, and TBC1D15 were identified in melanoma." (PMID 33194704, 2020). "Protein expression of TBC1D10C, TBC1D19, TBC1D16, and TBC1D13 were increased significantly in melanoma tissues." (PMID 33194704, 2020). "Interestingly, the role of TBC1D13 in melanoma remains unknown." (PMID 33194704, 2020).
TBC1D13 also shares sentences with these, for which no sentence is quoted: breast carcinoma (1 paper); Insulin resistance (1); skin cutaneous melanoma (1).